NLRP1 (NLR family pyrin domain containing 1)
Diseases named in the same sentence as NLRP1 in open-access papers (continued):
Sharing a sentence is not in itself a finding about the gene and the disease.
tumor (continued). "Therefore, in this study, we analyzed the correlations between NLRP1/NLRP3 and prognosis in patients with GC using experimental data and public databases, such as Oncomine, Tumor Immune Estimate Resource (TIMER), The Cancer Genome Atlas (TCGA), and Kaplan-Meier Plotter." (PMID 36541912, 2022). "Combined with the subsequent analysis, we got known that NLRP1 mainly affected tumor progression by regulating the immune microenvironment in tumor tissues, which may not play an essential role in promoting tumor distant metastasis." (PMID 33658393, 2021). "This suggested that NLRP1 and NLRP7 may be involved in tumour progression in LUAD." (PMID 34226539, 2021). "Because the mechanisms through which NLRP1 and NLRP3 regulate tumor immune infiltration in GC are not clear, we performed GSEA, which revealed the potential biological pathways involving NLRP1/NLRP3." (PMID 36541912, 2022). "We found that NLRP1 had opposite expression differences in two GC datasets, whereas NLRP3 showed no differential expression between tumor and normal tissues." (PMID 36541912, 2022). "However, because of a lack of studies of the mechanisms through which NLRP1 and NLRP3 regulate tumor immune cell infiltration in GC, more experimental studies are needed." (PMID 36541912, 2022).
cancer (58 papers, 2012 to 2025). A tumor composed of atypical neoplastic, often pleomorphic cells that invade other tissues. "We identified a significant correlation between NLRP1 expression and various cancer survival parameters, genetic mutations, and immune infiltration of cancer‐associated fibroblasts." (PMID 40237399, 2025). "CHOL emerged as the only cancer type displaying an association between NLRP1 downregulation and poor DFS." (PMID 40237399, 2025). "These associations suggest the potential utility of NLRP1 as a promising diagnostic, prognostic, and predictive biomarker in diverse cancers, providing valuable insights for personalized treatment strategies." (PMID 40237399, 2025). "In fact, NLRP1 was associated with autoimmune skin and lung disorders, arthritis, neurodegenerative disease, and cancer." (PMID 39684769, 2024). "So the NLRP1 expression level was significantly affected by the mutation status of several cancer-related genes with high mutation probability in LUAD." (PMID 33658393, 2021). "NLRP1 gain-of-function mutations have been demonstrated to contribute to constitutive inflammasome activation and IL-1β signaling in skin inflammation and cancer development." (PMID 33396632, 2020). "According to the dysregulation of NLRP1 in various malignancies, we postulate that its expression may be associated with the survival of patients with cancer." (PMID 40237399, 2025). "Additionally, studies have investigated the correlation between NLRP1 and various survival metrics, infiltration of cancer‐associated fibroblasts, genetic alterations, drug sensitivity, and promoter methylation." (PMID 40237399, 2025). "A comprehensive bioinformatic analysis was conducted to determine whether NLRP1 exhibits prognostic relevance linked to immune metabolism across various cancers." (PMID 39318060, 2024). "However, this study shows that NLRP1 mutations can be used as a reliable biomarker for the prognosis with good biological characteristics and better prognostic value in pan‐cancer." (PMID 39318060, 2024). "Both NLRP3 and NLRP1 are highly expressed in myeloid cell lines supporting findings of this study, yet it is known that germline NLRP1 mutations mainly manifest in skin inflammatory and cancer susceptibility." (PMID 37569318, 2023). "In addition, the mutation status of several cancer-related genes with high mutation probability in LUAD significantly affected the expression of NLRP1." (PMID 33658393, 2021). "This unexpected finding may suggest a predisposing effect of NLRP1 to cancer development: this could be explained considering the distribution of NLRP1 throughout the body and the unique role of NLRP1 in apoptosis." (PMID 23031505, 2012). "Furthermore, we have identified potential molecular mechanisms through which NLRP1 may influence cancer‐associated fibroblast immune infiltration, immune cell functionality, and participation in cancer progression." (PMID 40237399, 2025). "In addition, the association analysis between the gene alterations of NLRP1 and the clinical survival prognosis of pan‐cancer cases in the TCGA illustrates that the cases with the NLRP1 mutation has a good prognosis in OS (N = 10,803, p = 1.929e‐3) and DSS (N = 10,258, p = 1.355e‐3)." (PMID 39318060, 2024). "Reduced NLRP1 expression contributes to cancer progression and holds potential as a crucial biomolecular marker for diagnostic, prognostic, and personalized therapeutic interventions across different malignancies." (PMID 40237399, 2025). "For the differential expression analysis of NLRP1 in various cancer types compared to normal tissues, we used the TIMER2.0, starBase, GEPIA2, and UALCAN databases." (PMID 40237399, 2025). "NLRP1, a key component of the inflammasome complex, has emerged as a significant factor in cancer development." (PMID 40237399, 2025).
cancer (continued). "Nod‐like receptor family pyrin domain containing 1 (NLRP1) serves as the central component of the inflammasome complex and has emerged as a potential contributor to cancer development." (PMID 40237399, 2025). "Several databases have evaluated NLRP1 expression across various cancer types in The Cancer Genome Atlas (TCGA)." (PMID 40237399, 2025). "Despite accumulating evidence, a comprehensive assessment of NLRP1 across various cancer types has yet to be undertaken." (PMID 40237399, 2025). "Considering the significant role of NLRP1 in cancer pathogenesis and the existing uncertainty surrounding its alterations in various cancers, this study was undertaken." (PMID 40237399, 2025). "This downregulation is generally associated with poor prognosis, highlighting the significance of NLRP1 in cancer progression and patient survival." (PMID 40237399, 2025). "According to TIMER2.0, NLRP1 mRNA expression exhibited a notable decrease in cancerous tissues across multiple cancer types when compared to their respective healthy counterparts." (PMID 40237399, 2025). "Consistent with prior research, our results demonstrate the potential of NLRP1 as a prognostic biomarker in various types of cancer." (PMID 40237399, 2025). "Our comprehensive pharmacogenomic assessment revealed a significant correlation between reduced expression of the NLRP1 gene in cancer patients and enhanced sensitivity to a spectrum of chemotherapeutic and targeted agents." (PMID 40237399, 2025). "Strikingly, the immune microenvironment analysis of NLRP1 shows that NLRP1 expression is positively correlated with 28 different types of TILs with statistical significance in most types of cancers, including LUAD and PAAD." (PMID 39318060, 2024). "NLRP1 had the most significant change between paired cancer and adjacent tissue, which was significantly decreased in LUAD." (PMID 39258674, 2024). "When activated, formation of NLRP1 inflammasome leads to the production of proinflammatory cytokines to augment neurological disorders, cardio-pulmonary diseases and cancer through promoting inflammation." (PMID 39411284, 2024). "NLRP1 differential expression analysis was conducted in the Sangerbox 3.0 webserver to investigate the expression of NLRP1 in pan‐cancer." (PMID 39318060, 2024). "These insights not only enhance our understanding of NLRP1's involvement in cancer but also highlight its potential as both a therapeutic target and prognostic marker." (PMID 39318060, 2024). "NLRP3, NOD2, and NLRP1 were all highly expressed in primary tumors, further validating the protective role of PRGs in inhibiting cancer metastasis." (PMID 38697992, 2024). "Consistently, immunohistochemistry (IHC) staining also revealed significantly down-regulated expression of NLRP1 in cancer compared with adjacent tissue, using both The Human Protein Atlas (THPA) and our collected 3 paired LUAD tissues and adjacent tissue." (PMID 39258674, 2024). "NLRP1 has been demonstrated to increase the growth of cancer cells by inducing inflammasome activation and suppressing apoptotic pathways." (PMID 38990306, 2024). "Further, it was found that cancer cells with NLRP1 overexpression exhibited a much higher apoptosis rate (nearly doubled)." (PMID 39258674, 2024). "Overall, the clinical significance of NLRP1 in cancer is important, and this study lays the foundation for future research and applications." (PMID 39318060, 2024). "To confirm that the inflammasome pathway is playing a role in cancer cachexia, we assessed the gene expression of Nlrp1 and Nlrp3, which were increased in T7 and T14." (PMID 37177862, 2023). "The Gasdermin (GSDM) family member genes NLRP3, NLRC4, NLRP1, AIM2, IL-1β, and IL-18 are linked to TIME, and the immunosuppressive microenvironment can be overcome by targeted pyroptosis therapy in cancers." (PMID 36882663, 2023).
cancer (continued). "Here, we demonstrate that upregulation of p62 expression in SCC cells in vitro and in carcinomas represents a second pathway that antagonizes the NLRP1 inflammasome, suggesting that NLRP1 suppression in SCCs is relevant for cancer development." (PMID 36581625, 2022). "Most importantly, patients with these mutations are predisposed to develop cutaneous SCCs, demonstrating a link between NLRP1-induced inflammation and cancer development in human skin." (PMID 36293159, 2022). "To find cancer-related alterations in cancer inflammasome, we analyzed frameshift mutations of NLRP (NLRP1, 2, 4 and 9) genes closely related to the inflammasome in GC and CRC in this study." (PMID 34257569, 2021). "This indicates that the expression of NLRP1 affected not only the prognosis but also the immune activation status of cancer tissues." (PMID 33658393, 2021). "Homozygous deletion of Nlrp1b was found in 75% of mice studied, whereas in humans NLRP1 or its downstream target CASP1 is deleted in 9% of cancers analyzed." (PMID 31780749, 2019). "Both results identify NLRP1 as an essential mediator of the host immune response during intestinal inflammation and cancer." (PMID 26437418, 2015). "Additionally, the analysis of DFS data demonstrated that decreased NLRP1 transcription levels correlated with poor prognosis in various cancers, including CHOL (p = 0.039, HR = 0.37), LUAD (p = 0.033, HR = 0.72), and PAAD (p = 0.00037, HR = 0.45)." (PMID 40237399, 2025). "Drug sensitivity analysis revealed that cancer patients with low‐expression levels of the NLRP1 gene demonstrated heightened sensitivity to SNX‐2112, Dabrafenib, Momelotinib, Dacarbazine, AZD7762, NSC632839, and Merck60 (r value < −0.2, FDR < 0.001) based on the findings from the CTRP dataset." (PMID 40237399, 2025). "In addition to the known mechanisms, how the p62 protein supports cancer development in different tissues, the negative regulation of NLRP1 expression by p62 mRNA mediated by miR-34a-5p represents a novel pathway in the development of cSCCs." (PMID 40593496, 2025). "However, the complexity of NLRP1's clinical significance across cancers underscores the need for comprehensive research to fully elucidate its mechanisms." (PMID 39318060, 2024). "NLRP1 may serve a critical innate immune regulator of cancers via promoting IL‐1β and IL‐18 secretion." (PMID 39318060, 2024). "Furthermore, external validation on three selected cancers confirms that NLRP1 is downregulated in LUAD, while upregulated in PAAD and KIRC." (PMID 39318060, 2024). "Besides, several recent studies found that cancer with low NLRP1 expression had low immune cell infiltration and a poorer prognosis, which is consistent with our results." (PMID 37620327, 2023). "A better understanding of the complex functions of NLRP1 in the development of cSCCs and in general of inflammasomes in cancer might pave the way for novel strategies for cancer prevention and therapy." (PMID 36293159, 2022). "Specifically, high expression of NLRP1 was significantly correlated with poor OS in patients with stages 1–3 cancer (p = 0.048, p = 0.004, p = 0.0002), whereas high expression of NLRP3 was only correlated with poor outcome in patients with stage 3 GC (OS, p = 0.0003; FPS, p = 0.021)." (PMID 36541912, 2022). "It is likely that the function of NLRP1 differs in various cancers." (PMID 35574984, 2022). "Overall, the NLRP3, PJVK, TIRAP, IL18, NLRP1 and NLRP6 genes were thought to protect against cancer, while the rest of the pyroptosis genes seemed to be correlated with cancer risk." (PMID 35246158, 2022). "Due to its accessibility, pharmacological targeting of NLRP1 activation in epidermal keratinocytes represents a promising strategy for the treatment of the numerous patients suffering from NLRP1-dependent inflammatory skin conditions and cancer." (PMID 32640751, 2020). "Thus, the anti‐cancer potential of NLRP1 and CARD8 inflammasome activation also warrants further study." (PMID 32558991, 2020).
cancer (continued). "This ATF4/NLRP1 axis may also be a common molecular mechanism behind cancer resistance to other therapeutic approaches." (PMID 33396632, 2020). "Similarly, time-dependent NLRP1 up-regulation was observed in HeLa epithelial cancer cells that have very low NLRP1 mRNA basal levels." (PMID 26086088, 2015). "Moreover, the expression of NLRP1 exhibited correlations with DSS in various human cancers." (PMID 40237399, 2025). "Taken together, these data identify NLRP1 as an essential mediator of the host immune response during IBD and cancer." (PMID 40002872, 2025). "Moreover, the cell cycle of NLRP1-overexpressing cancer cells might be arrested in G1 phase." (PMID 39258674, 2024). "NLRP1, NLRP3, NLRC4, NLRP6, and AIM2 have been demonstrated to influence the pathogenesis of cancer by modulating innate and adaptive immune responses, cell death, and proliferation." (PMID 39684769, 2024). "High miR-335-5p expression promotes bone formation and regeneration and angiogenesis and regulates cancer progression by targeting MAPK10 or NLRP1/7." (PMID 37082197, 2023). "Protein kinase CAMP-activated catalytic subunit alpha (PRKACA), elastase neutrophil expressed (ELANE), NLRP1, pejvakin (PJVK), and CASP9 were significantly downregulated in 25, 24, 22, 25, and 23 types of cancers, respectively." (PMID 35246158, 2022). "As a critical regulator of multiple cancers, silencing of HOTTIP leads to suppression of cell proliferation and NLRP1 inflammasome-mediated pyroptosis." (PMID 36506086, 2022). "BCL2L1 inhibits caspase-1 activation by interfering with NLRP1 oligomerization, a key component of the inflammasome immune response, and ITP3 has an anti-apoptotic effect in mammalians cancer cells." (PMID 33676414, 2021). "Of the NLRs, NLRP1, NLRP3, NLRC4 and NLRP6 impact on the pathogenesis of cancer by regulating innate and adaptive immune responses, cell death and proliferation." (PMID 33658393, 2021). "The NLR family (NLRP1, NLRP3, NLRC4, NLRP6, and NLRP12) and their binding partners have mixed roles in the pathogenesis of a variety of cancers." (PMID 33584697, 2020). "NLRP1, NLRP3, NLRC4, NLRP6, NLRP7, and NLRP12 have mixed roles in the pathogenesis of a variety of cancers as reviewed here in details." (PMID 33584697, 2020). "Of these, NLRP1, NLRP3, NLRC4, NLRP6, and AIM2 influence the pathogenesis of cancer using various mechanisms of action." (PMID 33614494, 2020). "Conversely, NLRP1 was found to be overexpressed, particularly in CHOL and HNSC cancer types." (PMID 40237399, 2025). "NLRP1 is an NLR family protein that can also induce apoptosis and pyroptosis, which can impact cancer pathogenesis by modulating congenital immune responses, dysregulation of NLR family members, and results in various inflammatory diseases and autoimmune disorders." (PMID 35669428, 2022). "Consequently, treatment of cells with the anti-cancer drug and DPP8/9 active site inhibitor talabostat (Val-boroPro, PT-100) induces NLRP1 activation in human keratinocytes and the downstream secretion of high levels of IL-1β." (PMID 36293159, 2022). "There are nucleotide repeats in coding DNA sequences of NLRP1, 2, 4 and 9, which could be altered in MSI cancers." (PMID 34257569, 2021). "Although VbP did not activate NLRP1 in these cancer cell lines, perhaps due to low NLRP1 expression, VbP was subsequently found to induce NLRP1‐dependent pyroptosis in keratinocytes." (PMID 32558991, 2020). "Nevertheless, a systematic assessment of NLRP1's role across various cancer types currently absent." (PMID 39318060, 2024). "Because NLRP1 expression and IL-1β secretion are downstream mediators of TMZ-induced Notch activation, inhibiting NLRP1 and/or IL-1β could be used to regulate cancer aggressiveness and drug resistance, as we have shown in the current study." (PMID 32899791, 2020).